ALK (ALK receptor tyrosine kinase)
Diseases named in the same sentence as ALK in open-access papers (continued):
Sharing a sentence is not in itself a finding about the gene and the disease.
lung cancer (continued). "Importantly, these findings broadly applied to lung cancers with various RTK/MAPK pathway alterations — including EGFR mutations, ALK fusions, or KRASG12C mutations." (PMID 38483480, 2024). "Interestingly, ALK fusions are identified in most lung cancers, and ALCLs occur at the beginning of Exon 20 of the ALK gene." (PMID 39171208, 2024). "However, in the IAC cohort, the frequency of ALK fusion increased to 3.3% (10/303), suggesting that ALK fusions are more common in advanced-stage lung cancer." (PMID 39583122, 2024). "In addition to reporting the identification of a novel ALK fusion, XPO1-ALK (intergenic), and the sensitivity and safety of brigatinib treatment for lung cancer, this study increased the list of known ALK fusion partners in ALK-positive NSCLC." (PMID 39911820, 2024). "This case underscores that a dual-target therapy involving ALK inhibitors, specifically ensartinib and pralsetinib, could be a viable approach in cases of RET-rearranged lung cancer with concurrent targetable ALK mutations." (PMID 38698976, 2024). "Exon 19-containing ALK fusions have been rare in lung cancers and other ALK-positive tumors." (PMID 39171208, 2024). "Furthermore, lung cancer specimens and cell lines that developed resistance to ALK inhibitors exhibited increased PD-L1 expression, linking the PD-1/PD-L1 pathway to ALK inhibitor resistance in cases of ALK rearrangement." (PMID 38835380, 2024). "For example, the first-generation ALK inhibitor crizotinib, as well as second- and third-generation drugs such as brigatinib, lorlatinib, alectinib, and ceritinib, have been included in guidelines for the treatment of lung cancer patients with ALK gene fusions." (PMID 39906487, 2024). "ALK rearrangement is the first somatic oncogene translocation discovered in lung cancer." (PMID 37940761, 2024). "However, ALK rearrangements have been identified in approximately 5% of lung cancer patients, almost all of which are non-small-cell lung cancer (NSCLC)." (PMID 39781173, 2024). "To understand whether these findings could extend to other types of lung cancer bearing different driver mutations, we tested models of ALK+ lung cancer (NCI-H3122 cells) and KRASG12C mutant lung cancer (NCI-H358 cells)." (PMID 38483480, 2024). "As the most common fusion genes in lung cancer, ALK, RET, and ROS1 were selected for analysis." (PMID 38229122, 2024). "ALK translocations, discovered in the year 2007, account approximately for 5% of lung carcinomas." (PMID 38966170, 2024). "The absence of E-cadherin expression and the presence of vimentin expression suggest that this ALK-rearranged lung cancer may have undergone epithelial-mesenchymal transition, resulting in the loss of cellular adhesiveness." (PMID 37920641, 2023). "Chen’s study demonstrated that MR imaging based radiomic analysis of BM in patients with primary lung cancer may be used to classify EGFR, ALK, and KRAS mutation status and the AUC values based on cross validation was 0.912, 0.915, and 0.985, respectively." (PMID 38027000, 2023). "The role of tumor-infiltrating immune cells and the potential routes for successful immunotherapies in NSCLC is actively studied, which is also of interest in the ALK-rearranged subset of lung cancers because immune-based therapies showed limited efficacy in this cancer type." (PMID 37511126, 2023). "Clinicopathologic feature in lung cancer patients with ALK rearrangements by DNA‐based NGS." (PMID 36423218, 2023). "ALK rearrangement, EGFR mutation, and PDL‐1 testing are all recommended as part of molecular testing for metastatic NSCLC by NCCN in light of the significance of directed treatment for the overall control of lung cancer." (PMID 36971312, 2023). "Also known as CH5424802, this is an orally available selective ALK inhibitor already approved by the FDA for lung cancer treatment." (PMID 36839989, 2023). "ALK rearrangement is detectable in 2–7% of the lung cancer population." (PMID 37444532, 2023).
lung cancer (continued). "Therefore, it is imperative to establish a more feasible and effective strategy for ALK-positive lung cancer patients." (PMID 37221218, 2023). "The results demonstrated that LCOs from patients with EGFR-mutated lung cancer were sensitive to EGFR-TKI but not to ALK inhibitors." (PMID 37508518, 2023). "We present a rare case of Anaplastic Lymphoma Kinase (ALK)-rearranged lung cancer characterized by isolated scattered mucin-free cancer cells forming no clusters in the cytology of endobronchial ultrasound-guided transbronchial needle aspiration (EBUS-TBNA) samples from a paratracheal lymph node." (PMID 37920641, 2023). "One of the lung cancer brain metastases samples has been examined without rearrangements of ALK and ROS1 and EGFR mutation." (PMID 37479733, 2023). "Moreover, in all the H3122 lung cancer cell line samples bearing the EML4::ALK fusion, CircFusion detected f-circA22-E4 (5–17 reads per sample, average dataset depth of 15 M read pairs)." (PMID 36585787, 2023). "Patients with ALK-positive lung cancer may have specific clinicopathological features, including younger age, lower frequency of moderate cell differentiation, and higher frequency of the mucinous type." (PMID 36823653, 2023). "This differs from other commonly expressed lung cancer mutations such as in ROS1, anaplastic lymphoma kinase (ALK), and the epidermal growth factor receptor (EGFR) which have all seen significant success and acceleration with targeted therapy development in the last decade." (PMID 38067288, 2023). "HER3 activation contributes to DTCs survival in ALK‐rearranged lung cancer treated with ALK‐TKIs." (PMID 37638338, 2023). "Despite the development and increased availability of new therapeutic drugs for lung cancer, ALK-targeted drugs show a varied spectrum of drug efficacy and resistance to various mutations, thus leaving lung cancer the leading cause of cancer-related mortality worldwide." (PMID 37993887, 2023). "Unecritinib also displayed notable growth inhibitory effects on several cancer cell lines carrying ALK rearrangements or mutations or overexpressing c-MET, with an IC50 of 180 to 378.9 nm for lung cancer cells and an IC50 of 23.5 nm for gastric cancer cells overexpressing c-MET." (PMID 37385995, 2023). "In addition, miR-342-3p and let-7e expression levels were downregulated, and E-cadherin was lost in lung cancers with ALK rearrangements." (PMID 36821071, 2023). "Furthermore, when propagated in immunocompetent mice, distinct ALK-driven lung cancer cells exhibit differences in the depth and duration of response to the ALK inhibitor, alectinib which correlate with the composition of the immune microenvironment." (PMID 36739466, 2023). "Lung cancers with ALK rearrangement represent less than 5% of all lung cancers." (PMID 37894307, 2023). "Therefore, further investigations are needed to understand the fully adaptive resistances in ALK-rearranged lung cancer." (PMID 36702855, 2023). "A recent study showed that massive enhancer remodeling plays a key role in acquired resistance to anaplastic lymphoma kinase (ALK) inhibitors and that panobinostat can induce chromatin remodeling in resistant cells to overcome acquired resistance to ALK inhibitors in ALK-positive lung cancer." (PMID 36740715, 2023). "Brigatinib has been approved for treating ALK-positive metastatic non–small cell lung cancer that has deteriorated after crizotinib treatment or is intolerant to crizotinib in 2017 as for the first-line treatment of ALK-positive metastatic non–small cell lung cancer in 2020." (PMID 37196766, 2023). "At the same time, STAS was also found to be more frequently observed in ALK-rearranged lung cancer." (PMID 36816028, 2023). "Next, to explore whether EGFR activation reduced sensitivity to ALKi, ALK‐rearranged lung cancer cells were cotreated with the EGFR ligand EGF and ceritinib." (PMID 36423211, 2023).
lung cancer (continued). "Moreover, SHP2 mediates the activation of several receptor tyrosine kinases and downstream effectors of multiple signaling pathways (e.g., ALK-MAPK, PI3K/AKT/mTOR), and has been identified as a common resistance node in subsets of ALK-rearranged lung cancers." (PMID 38032104, 2023). "Lung cancer is driven by different molecular alterations, including the epidermal growth factor receptor (EGFR) mutations and the rearrangements of the anaplastic lymphoma kinase (ALK) and the c-ros1 (ROS1) genes." (PMID 37340403, 2023). "These treatments are currently recommended as a first-line therapy for ALK lung cancer." (PMID 37894307, 2023). "The objective of this study was to investigate whether the combination of a SHP2 inhibitor (SHP099) with alectinib would synergistically suppress the growth of ALK-positive lung cancer cells." (PMID 37339995, 2023). "Similarly, ALK inhibitors, such as crizotinib and ceritinib, block the activity of the ALK protein, which is often altered in lung cancer." (PMID 37741993, 2023). "Several ALK tyrosine kinase inhibitors (TKIs), if administered as first-line treatment, can effectively suppress the oncogenic activity of ALK rearrangement and improve the outcomes of advanced ALK-positive lung cancer patients." (PMID 37007097, 2023). "Studies have shown that normal doses or high doses of EGFR-TKI and ALK-TKI can alter the immune microenvironment in lung cancer, but whether immune activation or immune suppression occurs needs to be further explored." (PMID 37901223, 2023). "Alectinib, Brigatinib, and Lorlatinib are the preferred options but, in the absence of head-to-head comparisons, the optimal choice for first-line therapy in ALK-rearranged lung cancer remains unclear." (PMID 37444532, 2023). "However, evidence from ALK fusion-positive lung cancer studies has shown that resistance to ALK inhibition arises during the therapy, causing a relapse within several years." (PMID 37765276, 2023). "ALK tyrosine kinase inhibitors (TKI) are effective in patients with ALK-positive lung cancer." (PMID 37749521, 2023). "Importantly, the combination of lorlatinib and erlotinib effectively suppressed the adaptive survival of ALK-rearranged lung cancer cells by enhancing apoptosis induction via suppression of Bcl-xL." (PMID 36702855, 2023). "In all, 8398 (98%) were adults and 195 (2%) were children; 7865 patients (92%) were treated for lung cancer, of whom 7270 (92%) had an ALK rearrangement, 290 (4%) had an ROS1 rearrangement and 305 (4%) had another molecular abnormality, such as in RET, MET, or NTRK." (PMID 37894307, 2023). "In March 2021, a biopsy confirmed the presence of the ALK fusion gene in lung cancer." (PMID 37113357, 2023). "Patients with ALK-positive lung cancer may have clinicopathological features, including younger age, lower frequency of moderate cell differentiation, and higher frequency of the mucinous type." (PMID 36823653, 2023). "Young lung cancer patients have a different profile, as many young lung cancer patients are never smokers, have actionable mutations (most common being ALK and EGFR), and have predominantly adenocarcinoma histology." (PMID 37700839, 2023). "This budget may double in the case of NSCLC analysis, because lung carcinomas have to be additionally tested for EGFR, BRAF, KRAS, MET, and HER2 mutations as well as ALK, ROS1, and RET translocations." (PMID 37762506, 2023). "Since EML4-ALK V3, but not V1, is sequestered to microtubules in the presence of ALK-TKIs, we tested whether the addition of vincristine could enhance the cytotoxicity of ALK-TKI (crizotinib or ceritinib) in ALK-positive lung cancer cell lines." (PMID 35159046, 2022). "Hence, BCL-XL is necessary for the survival of ALK-rearranged lung cancer cells upon ALK inhibition." (PMID 35228642, 2022).
lung cancer (continued). "Twelve (18%) patients had KRAS mutation, two patients were EGFR mutation‐positive (3%), one patient had a BRAF mutation (2%) and no patient had lung cancer that was ALK mutation‐positive." (PMID 34196124, 2022). "Therefore, STAT3 mediates adaptive survival of ALK-rearranged lung cancer cells through evasion of apoptosis." (PMID 35228642, 2022). "NSCLC comprises of 85% of lung cancer cases and is characterized by diverse gene mutations, including epidermal growth factor receptor (EGFR), B-Raf oncogene (B-RAF), and anaplastic lymphoma kinase (ALK)." (PMID 35745617, 2022). "We next examined ALK-TKI responses on these six lung cancer cell lines." (PMID 35159046, 2022). "Among the detected alternations, the eight-major driver mutations of lung cancer (EGFR, ALK, ERBB2, MET, RET, ROS1, BRAF, and KRAS) could be found in 14 out of 17 (82.4%) patients using both surgical and CNB specimens." (PMID 36224661, 2022). "Furthermore, the inhibition of HER3 signals combined with ALK-TKIs dramatically improves treatment outcomes for ALK-rearranged lung cancer with mesenchymal features." (PMID 35042943, 2022). "Depicting the heterogeneity of ALK lung cancers, there have been more than 50 ALK KDMs described in the literature, with the expected ALKi clinical cross-resistance of these mutations to different ALKi’s becoming better established, with preclinical data informing the expected performance." (PMID 36003760, 2022). "Moreover, work by Bivona and colleagues has shown that genetic activation of STAT3 partially rescued ALK-rearranged lung cancer cells from the effects of ALK inhibitor treatment, with greater dependence on the RAS-MAPK pathway." (PMID 35228642, 2022). "As clinical studies have indicated that crizotinib or ceritinib therapy could reduce chest, arm, and shoulder pain in non–small cell lung cancer patients, it will be important to confirm that ALK inhibition is analgesic in human patients." (PMID 35608912, 2022). "In treatment-naïve lung cancer, oncogenic driver mutations, such as epidermal growth factor receptor (EGFR), Kirsten rat sarcoma virus (KRAS), BRAF, anaplastic lymphoma kinase (ALK), and ROS1, typically occur as trunk mutations with little intratumoral heterogeneity." (PMID 35008406, 2022). "ALK inhibitors are established as first-line therapies for lung cancers with ALK alterations." (PMID 36337169, 2022). "The less frequent EML4(e21)::ALK(e20) variant is not covered by the Idylla’s fusion-specific detection, which is designed to catch the most relevant gene fusions in lung cancer." (PMID 35237889, 2022). "Our results indicate that inhibition of the adaptive survival via STAT3 combined with an ALK-TKI may improve the outcomes of ALK-rearranged lung cancer." (PMID 35228642, 2022). "The combinational efficacy of YHO-1701 was abolished by BCL-XL overexpression, demonstrating that BCL-XL influences STAT3-mediated adaptive survival and that its downregulation is necessary for inducing apoptosis in adaptive ALK-rearranged lung cancer cells and eradicating residual tumors." (PMID 35228642, 2022). "We propose that clinically approved ALK inhibitors used for non–small cell lung cancer and neuroblastomas could be repurposed to treat persistent pain conditions." (PMID 35608912, 2022). "Finally, ALK inhibitors are FDA-approved therapeutics that perform well in other carcinomas (e.g. lung cancer)." (PMID 36129915, 2022). "Moreover, we attempted to develop a novel therapeutic strategy and identify a predictive biomarker for the prevention of DT cell emergence following ALK-TKI intervention, owing to the eradication of tumor activity in ALK-rearranged lung cancer." (PMID 35042943, 2022).
lung cancer (continued). "Parallel functional studies, in particular in tumor-derived organoids or vascularized co-culture systems, may help determine the specific contributions of candidate serine proteases to vascular remodeling and angiogenesis in ALK+ lung cancer." (PMID 36192379, 2022). "NSCLC accounts for around 80% of lung cancers, with ALK+ NSCLC accounting for 3%–7% of these." (PMID 35463328, 2022). "Furthermore, other pre-clinical studies have demonstrated that the inhibition of autophagy can overcome the emergence of resistance to tyrosine kinase inhibitors in NSCLC and ALK-positive lung cancer." (PMID 35600411, 2022). "Recent advances in cancer biology and genomics research have allowed an in-depth characterization of lung cancers that have revealed new therapy targets (EGFR, ALK, ROS, and KRAS mutations) and have the potential of revealing even more biomarkers for diagnostic, prognostic, and targeted therapies." (PMID 35628157, 2022). "Herein, we report a case of double primary lung cancers with ALK rearrangement." (PMID 35677159, 2022). "In ALK + lung cancer, there is a higher incidence of MUC1 and MUC5AC cytoplasmic expression, which, combined with a paucity of MUC2 and MUC6 expression, could lead to the biological aggressiveness of ALK + cancer." (PMID 36059804, 2022). "The median overall survival (OS) exceeds 80 months for ALK-positive lung cancer." (PMID 35806325, 2022). "For example, the ceritinib capsule is a targeted drug for lung cancer (the target gene is ALK)." (PMID 35711917, 2022). "Hence, this study provides new insights into combined therapeutic strategies for patients with ALK-rearranged lung cancer." (PMID 35228642, 2022). "Mutations in lung cancer driver genes (KRAS, EGFR, BRAF, ALK, ROS1, MET, RET, and ERBB2) in the high- and low-risk groups were shown on a waterfall plot, which demonstrated that the low-risk group (20%) harbored a higher EGFR mutation frequency than did the high-risk group (8%)." (PMID 36353226, 2022). "Interestingly, our results showed that the risk of VTE in ROS1 rearrangements(ROS1+) patients is 2.63-fold greater than that in ROS1- patients, and the odds of VTE in ROS1+ lung cancer were higher than ALK+, EGFR+ and KRAS+ cohorts in the univariate analysis." (PMID 36300098, 2022). "Based on our results, we conclude that EML4-ALK may be useful for predicting potential responses to ALK inhibitors used as therapeutic options for patients with lung cancer." (PMID 36185247, 2022). "EGFR or ALK gene status is included in the amendment of lung cancer score, lung-molGPA." (PMID 35558520, 2022). "EML4-ALK fusion is the most common fusion pattern in ALK-positive lung cancers." (PMID 35627126, 2022). "METex14 skipping mutation is considered to be an independent lung cancer driver, which is usually mutually exclusive with other lung cancer driver genes such as EGFR, ALK and ROS1, and is also associated with poor prognosis of lung cancer, including sarcomatoid cancer." (PMID 36212500, 2022). "Although EGFR, KRAS, and ALK mutations are generally considered mutually exclusive in NSCLC, recent studies have shown that above oncogenic driver mutations can co-exist in a certain amount of lung cancers." (PMID 36376839, 2022). "After the discovery of ALK rearrangement in lung cancer, the first-in-class ALK inhibitor crizotinib was shown to be superior to standard first-line chemotherapy in patients with previously untreated advanced ALK-positive NSCLC." (PMID 36004269, 2022). "DCTN1 has been identified as an anaplastic lymphoma kinase (ALK) fusion partner in lung cancer." (PMID 36291758, 2022). "“Direct STAT3 inhibition” may be more effective for suppressing treatment-induced STAT3 activation and the subsequent adaptive survival of ALK-rearranged lung cancer cells." (PMID 35228642, 2022).